CCN1 (cellular communication network factor 1)
Diseases named in the same sentence as CCN1 in open-access papers (continued):
Sharing a sentence is not in itself a finding about the gene and the disease.
breast tumors (9 papers, 2012 to 2024). "In breast tumors, both the steroid-dependent proteins CCN1 and CCN2 are overexpressed; these proteins are also estrogen-inducible." (PMID 34940056, 2021). "As a chemotherapeutic agent, ZOL is found to inhibit breast tumor formation, proliferation and metastasis to the bone by inhibiting CCN1 expression and FOXO3a activation." (PMID 34940056, 2021). "CCN1/CYR61 might promote enhanced angiogenesis and deregulated proliferation and chemoresistance in breast tumors by binding to and activating αvβ3 integrin signaling." (PMID 35148282, 2022). "Additionally, Cyr61 (CCN1), which promotes breast tumor angiogenesis, was down-regulated in the combinational treatment group compared to both untreated controls and vaccine alone." (PMID 31693710, 2019).
psoriasis (9 papers, 2017 to 2025). An autoimmune condition characterized by red, well-delineated plaques with silvery scales that are usually on the extensor surfaces and scalp. "CCN1 is a secreted ECM protein, and research has shown that blocking CCN1 function in vivo can effectively alleviate epidermal hyperplasia and inflammation in psoriasis-like mice." (PMID 36832881, 2023). "This suggests that CCN1 plays a role in the pathogenesis of psoriasis and in modulating inflammation in the disease." (PMID 30744173, 2019). "Overall, we showed that CCN1 increased IL-1β production via p38 MAPK signaling, indicating a role for CCN1 protein in regulating inflammation in psoriasis." (PMID 28266627, 2017). "To confirm these results in vivo, we further blocked CCN1 with a monoclonal antibody or a lentiviral vector expressing shRNA in IMQ-/IL-23-induced psoriasis-like mice and found impaired IL-1β expression following CCN1 silencing." (PMID 28266627, 2017). "First, we established an IMQ-induced psoriasis-like mouse model and knocked down CCN1 expression with the monoclonal antibody 093G927." (PMID 28266627, 2017). "In our previous study, we found that CCN1 was highly expressed in the lesional skins of psoriasis patients and was involved in the pathogenesis of psoriasis by promoting keratinocyte activation." (PMID 28266627, 2017). "In contrast, the level of CCN1 is elevated in the entire epidermis of the lesional skin of psoriasis patients and promotes the production of Interleukin-8 (IL-8), IL-1β and C–C Motif Chemokine Ligand 20, which drives psoriatic inflammation and skin barrier disruption." (PMID 35046484, 2022). "We demonstrated in our previous study that CCN1 promoted keratinocyte activation in psoriasis." (PMID 28266627, 2017). "This study suggests that the CCN1 protein might be a potential target for reducing inflammation in psoriasis." (PMID 28266627, 2017). "Thus, our results indicate that CCN1 not only directly activates keratinocytes but is also involved in the amplification cycle for the chronic inflammation of psoriasis by enhancing IL-1β expression." (PMID 28266627, 2017). "Given that IL-1β functions as an initiator and effector for inflammation and skin lesions in psoriasis, we investigated whether CCN1 contributes to IL-1β production in keratinocytes." (PMID 28266627, 2017). "In addition, we inhibited CCN1 function in mouse models of psoriasis, and decreased IL-1β production was observed in vivo." (PMID 28266627, 2017). "As CCN1 is considered as a pro-inflammatory factor in RA pathology, we further explored whether CCN1 contributed to the inflammation of psoriasis." (PMID 28266627, 2017). "However, whether CCN1, a novel pro-inflammatory factor, triggers inflammation in other autoimmune and inflammatory diseases, such as psoriasis, was unknown." (PMID 28266627, 2017). "Then, we investigated whether CCN1 regulated IL-1β production in mouse models of psoriasis." (PMID 28266627, 2017). "However, the role of CCN1 in regulating inflammation in psoriasis is still unclear." (PMID 28266627, 2017). "To confirm these results, we blocked CCN1 function with a monoclonal antibody in imiquimod (IMQ)-induced psoriasis-like mice or with a lentiviral vector expressing short hairpin RNA (shRNA) in IL-23-induced psoriasis-like mice, and we also found impaired IL-1β expression in vivo." (PMID 28266627, 2017). "Thus, we concluded that CCN1 increased IL-1β production via p38 MAPK signaling in keratinocytes, suggesting that CCN1 might be a potential target for ameliorating inflammation in psoriasis." (PMID 28266627, 2017). "CCN1, a novel proinflammatory factor and extracellular protein, increases IL-1β production via p38 MAPK signaling, thereby promoting inflammation in psoriasis." (PMID 41385507, 2025). "However, the role of CCN1 in regulating inflammation in psoriasis is still unknown." (PMID 28266627, 2017).
psoriasis (continued). "In conclusion, the present study reveals a novel mechanism for CCN1 in regulating IL-1β expression via p38 MAPK signaling in keratinocytes, which contributes to the inflammatory microenvironment of psoriasis." (PMID 28266627, 2017). "In addition, IL-36G upregulates the expression of CCN1 and S100A7A, leading to the production of excessive pro-inflammatory factors by the cells, including IL-1, IL-6, IL-8, IL-36, and TNF, which promotes psoriasis." (PMID 40735322, 2025).
myocardial infarction (8 papers, 2013 to 2024). Gross necrosis of the myocardium, as a result of interruption of the blood supply to the area, as in coronary thrombosis. "Some members of the matricellular protein family (like tenascin-C, osteopontin, CCN1 and the galectins) have been implicated in the inflammatory and reparative responses following myocardial infarction and may function as danger signals." (PMID 24363498, 2013). "In the heart, CCN1 expression is elevated in patients with myocarditis, dilated cardiomyopathy and myocardial infarction." (PMID 25446180, 2015). "CCN1 serves as an early biomarker for myocardial infarction, kidney injury, and liver I/R injury." (PMID 37695472, 2024). "CCN1 gene knockout mice showed higher ECM structural complexity in the scar area after myocardial infarction, including reduced local arrangement and increased curvature of collagen fibers, as well as a 90% decrease in tissue consistency, packaging, and size of collagen fibrils." (PMID 39568592, 2024). "However, further limited evidence suggests that CCN1 modulates the immune response to autoimmune myocarditis, with upregulated expression in response to myocardial infarction or pressure overload, which is recapitulated in tissue from patients with end-stage ischemia cardiomyopathy." (PMID 35163259, 2022). "CCN1/CYR61 is often studied along with CCN2/CTGF in mice models of cardiac infarction, where both CCNs are induced 12 o 14 weeks after induction of myocardial infarction." (PMID 34063397, 2021).
pulmonary arterial hypertension (8 papers, 2019 to 2025). Pulmonary arterial hypertension (PAH) is a group of diseases characterized by mean pulmonary artery pressure >20 mmHg and elevated pulmonary arterial resistance leading to right heart failure. "Inconsistent with our results, it is reported that overexpression of CCN1 inhibited the NF‐κB signaling pathway in pulmonary hypertension." (PMID 39659236, 2024). "A study evaluated the expression of CCN1 in patients with pulmonary arterial hypertension (PAH), which belongs to the first type of PH." (PMID 33105556, 2020). "Additionally, Astragaloside IV has been shown to ameliorate pulmonary hypertension by enhancing CCN1 expression." (PMID 40811488, 2025). "And this phenomenon may elucidate the contrasting impacts of CCN1 on the NF‐κB pathway observed between pulmonary hypertension and GBM." (PMID 39659236, 2024). "We proposed that CCN1 was significantly upregulated in lung tissue following DHCA and primarily contributes to lung injury by exacerbating inflammation and inducing pulmonary hypertension." (PMID 40811488, 2025).
acute kidney injury (7 papers, 2017 to 2025). Sudden and sustained deterioration of the kidney function characterized by decreased glomerular filtration rate, increased serum creatinine or oliguria. "Wnt signaling and CCN1 have well-known roles in tissue and organ remodeling and repair, but also in inflammation, acute kidney injury, and other pathology development, suggesting their context-dependent functions." (PMID 38598837, 2024). "The potential of CCN1 as a biomarker is currently being investigated in diseases such as juvenile idiopathic arthritis (NCT05534347) and acute kidney injury (NCT05242705)." (PMID 40234387, 2025). "Intriguingly, CCN1 is a key protein in the transition from acute kidney injury (AKI) to CKD, and blockade of CCN1 can mitigate renal inflammation and fibrosis after ischemic reperfusion induced AKI." (PMID 33192525, 2020).
diabetic retinopathy (7 papers, 2014 to 2024). "CCN1 is closely associated with diabetic microangiopathy, particularly diabetic retinopathy." (PMID 37334311, 2023). "By suppressing CCN1 or abolishing NETs, retinal leakage can be significantly reduced, providing a novel insight into the treatment of diabetic retinopathy." (PMID 38755602, 2024). "To delve further into the relationship between CCN1 and the progression of diabetic retinopathy, we investigated whether CCN1 was involved in the progress of DR." (PMID 38755602, 2024). "Notably, manipulating CCN1 was able to hold therapeutic promise for the treatment of diabetic retinopathy." (PMID 38755602, 2024). "Collectively, these results suggest that CCN1 is upregulated in both retinas and peripheral blood under diabetic conditions, and the elevated levels of CCN1 may contribute to the progression of diabetic retinopathy." (PMID 38755602, 2024). "However, the precise role of CCN1 in microvascular occlusion and its potential interaction with neutrophils in diabetic retinopathy have not yet been investigated." (PMID 38755602, 2024).
autoimmune disease (6 papers, 2017 to 2022). A disorder resulting from loss of function or tissue destruction of an organ or multiple organs, arising from humoral or cellular immune responses of the individual to their own tissue constituents. "Recent studies have found that cysteine-rich protein 61 (Cyr61/CCN1) participates in the regulation of the inflammatory microenvironment and is involved in the pathology of inflammation and autoimmune diseases." (PMID 32774151, 2020).
liver cancer (6 papers, 2016 to 2023). An epithelial or non-epithelial malignant neoplasm that arises from the liver. "In addition, LINC00907 (logFC = −2.6057), CCN1 (logFC = −2.05925), GSTZ1 (logFC = −2.34197), and GSTM5 (logFC = −2.8954) were lowly expressed in liver cancer tissues." (PMID 36685007, 2023).
lung diseases (6 papers, 2013 to 2023). "As a communicator between lung parenchymal cells and inflammatory cells, as well as a connector between intracellular components and ECM, CCN1 indicated a potential cellular target for therapy development in a variety of lung diseases associated with CS." (PMID 23874538, 2013). "In the following sections, we present our current knowledge of CCN1 in various lung diseases and summarize the signaling pathways involved in their pathophysiology." (PMID 33105556, 2020). "Obviously, these effects of CCN1 are different in the same lung disease model." (PMID 36762748, 2023). "CCN1 is expressed in a variety of lung diseases, but its specific role is controversial." (PMID 36762748, 2023). "In conclusion, the effect of CCN1 is different in different lung disease models." (PMID 36762748, 2023). "We also emphasize the important challenges for future investigations to better understand the CCN1 and its role in physiology and pathology, as well as the questions that need to be addressed for the therapeutic development of CCN1 antagonists in various lung diseases." (PMID 33105556, 2020). "In this review, we focus on the CCN1 protein and its known roles in human lung diseases." (PMID 33105556, 2020).
Obesity (6 papers, 2018 to 2023). Accumulation of substantial excess body fat. "Treatment of skeletal muscle FAPs with CCN1/CYR61 leads to differentiation into adipocytes, which is linked to sarcopenic obesity in the CKD patients mentioned before." (PMID 34063397, 2021). "Our co-immunoprecipitation experiments demonstrated an increase in binding between CCN1 and integrin α5β1 in hepatocytes following FFA stimulation and during obesity in mice, indicating integrin α5β1 as a potential receptor for CCN1." (PMID 36145246, 2022). "CCN1/CYR61 expression is also increased in the serum of chronic kidney disease (CKD) patients, which present sarcopenic obesity, and in serum and skeletal muscle from a mouse model of CKD." (PMID 34063397, 2021).
systemic lupus erythematosus (6 papers, 2017 to 2025). An autoimmune multi-organ disease typically associated with vasculopathy and autoantibody production. "The effects of treatment with conditioned MD cell culture media (rich in CCN1) were tested in NZM.2328 BAFF transgenic lupus mice using intravital multiphoton microscopy, histology, and classic kidney function phenotyping." (PMID 40843448, 2025).
astrocytoma (5 papers, 2017 to 2022). "A previous study reported that integrin α5β1 mediates adhesion to CCN1 and thrombin-stimulated DNA synthesis in astrocytoma cells." (PMID 36145246, 2022). "High CCN1 expression correlated with high astrocytoma grade (e.g., 50% astrocytoma grade 4 samples were scored 4 or higher), while low CCN1 expression was observed within low astrocytoma grades." (PMID 35052688, 2021). "This indicates that the ZIKV infection of human astrocytoma CCF-STTG1 cells in vitro up-regulates CCN1 expression." (PMID 31957543, 2020). "However, Zika-induced CCN1 expression can promote virus replication in human astrocytoma cells (CCF-STTG1) cells." (PMID 35418961, 2022). "Quantification and comparison of the different brain tumour types revealed a clear correlation of high CCN1 expression with GBM (tumour grade 4) that was significantly different from the negative control and low-grade astrocytoma." (PMID 35052688, 2021).
bladder cancer (5 papers, 2016 to 2023). "IRF5 (p=0.055), CCN1 (p=4.1e-08), MYC (p=0.039), POU5F1 (p=0.027), and TGFB1I1 (p=6.5e-08) were significantly differentially expressed at different stages of bladder cancer." (PMID 37433010, 2023). "Similarly, in TCGA database bladder cancer samples, CCN1 (p=7.9e-07), MYC (p=0.0043), POU5F1 (p=0.021), and TGFB1I1 (p=6.0e-05) had significant differences in bladder cancer high-grade and low-grade samples, in addition to IRF5 (p=0.2)." (PMID 37433010, 2023).
chondrosarcoma (5 papers, 2013 to 2021). A malignant cartilaginous matrix-producing mesenchymal neoplasm arising from the bone and soft tissue. "Our early study highlighted CCN1 activated MMP-3 expression and cell migration through αvβ3 receptor and FAK/ERK/AP-1 in human chondrosarcoma." (PMID 25187949, 2014).
chronic kidney disease (5 papers, 2021 to 2024). Impairment of the renal function secondary to chronic kidney damage persisting for three or more months. "Human and therapeutic translation studies illustrated the clinical potential of MD factors, including CCN1, as a urinary biomarker and therapeutic target in chronic kidney disease." (PMID 38598837, 2024). "For instance, the matricellular protein CCN family member 1 (CCN1/CYR61) is elevated in the serum and sarcopenic muscles of a murine model of chronic kidney disease and induces FAP adipogenesis." (PMID 34210364, 2021).
colitis (5 papers, 2018 to 2023). Inflammation of the colon. "CCN1 is restricted to terminally differentiated intestinal cells in the normal colon but is found all over the crypt upon DSS treatment in a mouse colitis model." (PMID 38106420, 2023). "In the initiation phase of colitis, IL-6 upregulation is independent of CCN1, but later in the repair phase (8 days after DSS administration), IL-6 overexpression is mainly CCN1-dependent." (PMID 38106420, 2023).
Hyperglycemia (5 papers, 2008 to 2023). An increased concentration of glucose in the blood. "As both hyperglycemia and hyperlipidemia are the main metabolic features of DM, we investigated how hyperlipidemia affects CCN1 expression in ApoE−/− mice." (PMID 34458333, 2021). "However, the mechanism on how CCN1 is regulated by hyperglycemia or hyperlipidemia and how CCN1 regulates NOX4 expression remains unclear." (PMID 34458333, 2021). "Thus, CCN1 levels may reflect vascular damage caused by chronic hyperglycemia, rather than glycemic control." (PMID 37334311, 2023).
Hypertension (5 papers, 2015 to 2026). The presence of chronic increased pressure in the systemic arterial system. "Here, we investigate the role of the matricellular protein CCN1 in hypertension-associated cognitive impairment and elucidate the potential neuroprotective mechanisms conferred by DIZE." (PMID 41860098, 2026). "We identify a novel CCN1-integrin αvβ6-TGF-β-mitochondrial dysfunction signaling axis as a key mediator of hypertension-induced cognitive impairment and demonstrate that DIZE confers neuroprotective effects through post-transcriptional suppression of CCN1 via accelerated mRNA degradation." (PMID 41860098, 2026).